NEDD4L (NEDD4 like E3 ubiquitin protein ligase)
Diseases named in the same sentence as NEDD4L in open-access papers (continued):
Sharing a sentence is not in itself a finding about the gene and the disease.
glioma (continued). "The upregulation of NEDD4L had tumor‐suppressing properties in glioma." (PMID 36052751, 2022). "To test this hypothesis that PF might function through the elevation of NEDD4L, we knocked down the NEDD4L in U87 glioma cells for 24 hours before subjecting these cells to PF treatment." (PMID 36618071, 2022). "Furthermore, our xenograft data demonstrated that PF can suppress glioma tumor growth by activating NEDD4L/STAT3/Nrf2/GPX4 signal axis which eventually triggers ferroptosis." (PMID 36618071, 2022). "Moreover, we found that NEDD4L was targeted by miR‐10b‐5p and that NEDD4L exhibited a low expression in glioma tissues." (PMID 36052751, 2022). "The data showed that NEDD4L is significantly downregulated in gliomas." (PMID 36618071, 2022). "Taken together, our data suggest that PF carries out its antitumor effect by regulating the expression of NEDD4L, which could further manipulate ferroptosis in glioma cells." (PMID 36618071, 2022). "In order to investigate whether NEDD4L regulates glioma cell proliferation through manipulating STAT3, we generated STAT3-overexpressing U251 glioma cells, and the overexpression of STAT3 was validated by both qPCR and western blot." (PMID 36618071, 2022). "As suggested by our previous data that a high level of NEDD4L improves the overall survival of glioma patients, we proposed to investigate whether the manipulation of NEDD4L affects glioma cell proliferation." (PMID 36618071, 2022). "In summary, this study demonstrated that paeoniflorin might function as an effective drug for glioma by inducing ferroptosis via upregulation of NEDD4L and repression of Nrl2, GPX4, and STAT3." (PMID 36618071, 2022). "We then carried out a coimmunoprecipitation (Co-IP) assay to determine whether STAT3 interacts with NEDD4L in glioma U251 cells." (PMID 36618071, 2022). "Contrary to the oeNEDD4L cells, proliferation is promoted in the NEDD4L-knockdown glioma cells." (PMID 36618071, 2022). "Therefore, this project aims to study the effect and mechanism of PF/NEDD4L/STAT3 on the proliferation of glioma." (PMID 36618071, 2022). "Downregulation of NEDD4L was also reported in glioma tissues." (PMID 34305532, 2021). "In addition, NEDD4L was reported as a direct target of miR-513a-5p, delayed the growth of glioma cells and amplified the cytotoxicity of temozolomide (TMZ)." (PMID 34869021, 2021). "This study reveals that NEDD4L mediates SphK2 ubiquitination to regulate glioma malignancy and may provide some meaningful suggestions for glioma treatment." (PMID 34305532, 2021). "Overexpression of SphK2 significantly promoted glioma growth, and this could be partially reversed following NEDD4L in combination with SphK2 overexpression." (PMID 34305532, 2021). "Moreover, NEDD4L overexpression induced the ubiquitination of SphK2 reversing the promotion of glioma cells mediated by SphK2." (PMID 34305532, 2021). "Furthermore, we next compared endogenous NEDD4L levels in normal astrocytes and three different glioma cell lines." (PMID 31805126, 2019). "Both the protein and mRNA levels of NEDD4L were lower in glioma cells than in primary astrocytes." (PMID 31805126, 2019). "Finally, our results suggest that IGF-1-upregulated miR-513a-5p signaling attenuated glioma cell sensitivity to TMZ via inhibiting NEDD4L-inactivated WNT/β-catenin pathways." (PMID 31805126, 2019). "After NEDD4L overexpression, the viability of both U87-MG and M059K cells was significantly and dose-dependently decreased, suggesting that NEDD4L acts as a tumor suppressor in glioma progression." (PMID 31805126, 2019). "IGF-1 treatment significantly reduced endogenous NEDD4L levels in glioma cells." (PMID 31805126, 2019). "Overexpression of NEDD4L significantly reduced glioma cell viability." (PMID 31805126, 2019). "Moreover, NEDD4L-mediated ubiquitination of SphK2 inhibits glioma cell survival and invasion." (PMID 38027016, 2023).
glioma (continued). "Moreover, multivariate analysis shows that NEDD4L expression is an independent prognostic factor in patients with gastric cancer, squamous lung cancer and glioma." (PMID 38027016, 2023). "Moreover, NEDD4L-mediated ubiquitination of SphK2 promotes glioma cell apoptosis." (PMID 38027016, 2023). "Therefore, we hypothesized that hypoxia‐stimulated glioma‐derived EVs harboring miR‐10b‐5p may affect the M2 polarization of macrophages through NEDD4L/PIK3CA/PI3K/AKT axis." (PMID 36052751, 2022). "Therefore, we speculated that NEDD4L could regulate glioma development via PIK3CA and PI3K/AKT pathway." (PMID 36052751, 2022). "In addition, Kaplan-Meier analysis showed that patients with NEDD4L-low-expressing glioma exhibit a worse prognosis compared with patients with NEDD4L-high-expressing glioma, which demonstrates the potential of NEDD4L function as a biomarker to predict the clinical outcome of glioma patients." (PMID 36618071, 2022). "Furthermore, overexpression of NEDD4L induces glioma cell death." (PMID 36618071, 2022). "The data suggested that paeoniflorin could increase NEDD4L expression in glioma cells." (PMID 36618071, 2022). "Consequently, NEDD4L mainly crippled the malignant biological behavior of glioma." (PMID 34869021, 2021). "Thus, we speculated that NEDD4L-mediated ubiquitination of the SphK2 protein might reverse its role in gliomas." (PMID 34305532, 2021). "Downregulation of NEDD4L increases PIK3CA expression, thereby promoting glioma cell proliferation by activating the PI3K/AKT pathway." (PMID 38027016, 2023). "The macrophages or glioma cells were transfected with overexpressing plasmid or shRNA to study the effects of miR‐10b‐5p/NEDD4L/PIK3CA on M2 macrophage polarization, and glioma cell proliferation, migration, and invasion in vitro and in vivo." (PMID 36052751, 2022). "In order to determine the interaction between NEDD4L and STAT3 in glioma cells, we engineered glioma U251 cells to overexpress NEDD4L, which was validated by both qPCR and western blot." (PMID 36618071, 2022). "Our study indicated the tumor‐promoting capacity of hypoxic glioma cell‐derived EVs harboring miR‐10b‐5p for glioma via upregulated PIK3CA and activated PI3K/AKT pathway through downregulating NEDD4L." (PMID 36052751, 2022). "Meanwhile, our results further confirmed that NEDD4L inhibits the PI3K/AKT pathway through PIK3CA to inhibit M2 polarization of macrophages, thereby restraining cell malignant phenotypes in glioma." (PMID 36052751, 2022). "NEDD4L, identified as a direct target gene of miR-513a-5p, was significantly downregulated in GBM patients and IGF-1-treated glioma cells." (PMID 31805126, 2019). "Moreover, in glioma cells, miR-10b-5p increases PIK3CA expression by downregulating NEDD4L expression, thereby promoting the proliferation, migration, and invasion of glioma cells by activating the PI3K-AKT pathway." (PMID 38027016, 2023). "In glioma, IGF‐1 could modulate miR‐513a‐5p expression to affect the NEDD4L/Wnt/β‐catenin signalling pathway and desensitize glioma cells to temozolomide." (PMID 32342645, 2020). "Also, insulin-like growth factor 1 stimulates glioma proliferation by upregulating miR-513a-5p which acts to suppress expression of NEDD4L via PI3K signaling; this in turn prevents NEDD4L from inhibiting Wnt/β-catenin signaling and promotes GBM progression and chemoresistance." (PMID 34337348, 2021). "In addition, lower levels of neural precursor cell-expressed developmentally downregulated 4-like (NEDD4L), an E3 ubiquitin protein ligase that inhibits WNT signaling, were found in gliomas by analyzing cells, arrays, and RNA sequencing data of TCGA glioma patients." (PMID 31805126, 2019).
glioma (continued). "However, the exact role of NEDD4L in glioma is still not fully elucidated." (PMID 36618071, 2022). "Furthermore, a negative correlation was identified between miR-513a-5p and NEDD4L in glioma." (PMID 31805126, 2019). "Immunohistochemical staining was used to confirm that NEDD4L protein expression was downregulated in LUAD, infiltrating ovarian epithelial tumor, hepatocellular carcinoma, renal cell carcinoma, rectal carcinoma, gastric cancer, and glioma compared to that in paraneoplastic or normal tissues." (PMID 38027016, 2023).
prostate carcinoma (21 papers, 2009 to 2025). A carcinoma that arises from epithelial cells of the prostate gland. "In a clinical study, it was reported that the loss of NEDD4L expression was frequently observed in prostate cancer patients with more aggressive tumors." (PMID 36293239, 2022). "For instance, decreased NEDD4L expression corresponds to an increased prostate cancer risk, while that in NSCLC corresponds with a poor prognosis." (PMID 31673244, 2019). "These two studies contradict the findings of other studies on the role of NEDD4L in prostate cancer and melanoma." (PMID 38027016, 2023). "NEDD4L inhibits the proliferation of prostate cancer cells by degrading plant homeodomain finger protein 8 (PHF8/KDM7B) through the ubiquitin–proteasome system." (PMID 38027016, 2023). "It was also shown that downregulation of NEDD4L significantly correlates with increased Gleason score, indicating the possibility of its role in prostate cancer progression." (PMID 36293239, 2022). "In prostate cancer and gastric cancer, NEDD4L promotes cancer cell proliferation and is positively associated with tumor progression." (PMID 35646490, 2022). "The expression of NEDD4L was decreased in prostate cancer specimens compared with benign prostatic hyperplasia." (PMID 34869021, 2021). "NEDD4L has also been found to be both upregulated and downregulated in prostate cancer, increased in invasive gallbladder cancer cells, and downregulated in more aggressive malignant gliomas." (PMID 24312311, 2013). "In prostate cancer cells, NEDD4L overexpression reduced its proliferation." (PMID 38526036, 2024). "Nonetheless, the role of NEDD4L in prostate cancer remains unclear, warranting further investigation." (PMID 38027016, 2023). "NEDD4L was also downregulated in androgen-independent prostate cancer cells." (PMID 34869021, 2021). "Interestingly, the expression of three NEDD4L transcripts, NEDD4Lf, NEDD4Lg and NEDD4Lh, was upregulated in prostate cancer cells after androgen administration." (PMID 34869021, 2021). "NEDD4L is down-regulated in prostate cancer, and may exert an antitumor function by regulating TGFβ1 signaling." (PMID 34458018, 2021). "The expression and functions of NEDD4L in prostate cancer are still ambiguous." (PMID 34869021, 2021). "In addition, one study reported that NEDD4L level was higher in prostate cancer tissues than in adjacent normal tissues, and NEDD4L might contribute to the development of prostate cancer by inhibiting the TGF-β signaling pathway." (PMID 38027016, 2023). "Furthermore, NEDD4L might contribute to the development of prostate cancer by reducing the TGF-β signaling pathway." (PMID 34869021, 2021). "A FISH probe targeting the NEDD4L (neuronal precursor cell expressed, developmentally down-regulated 4-like, 18q21) gene had been selected because it maps to the center of the often large 18q deletions in prostate cancer and it is one of the candidate tumor suppressor genes located on 18q." (PMID 27861151, 2016). "Several of the human NEDD4L transcripts are androgen sensitive in prostate cancer cell lines, but other extracellular cues have not been identified." (PMID 24147136, 2013). "Hence, the function of NEDD4L in prostate cancer is not clear." (PMID 34869021, 2021).
epilepsy (19 papers, 2016 to 2025). A brain disorder characterized by episodes of abnormally increased neuronal discharge resulting in transient episodes of sensory or motor neurological dysfunction, or psychic dysfunction. "NEDD4L, meanwhile, is an epilepsy-associated protein that regulates expression of the α-amino-3-hydroxy-5-methyl-4-isoxazolepropionic acid (AMPA) receptor subunit GluA1." (PMID 38731820, 2024).
gastric cancer (19 papers, 2013 to 2025). A primary or metastatic malignant neoplasm involving the stomach. "Research has confirmed that NEDD4L expression is increased in gastric cancer tissues and associated with a poor prognosis." (PMID 41561975, 2025). "Low-level expression of NEDD4L in gastric cancer is associated with aggressive metastatic disease and poor clinical outcomes, suggesting its role in the inhibition of metastasis through preventing EMT." (PMID 41385185, 2025). "In prostate and gastric cancers, deficient expression of NEDD4L contributes to a higher tumor grade and poor prognosis, suggesting that NEDD4L boosts the TGF‐β/Smad signaling to suppress tumorigenesis." (PMID 32259050, 2020). "Our previous experimental results indicate that NEDD4L is associated with tumor differentiation, invasion, and metastasis, and NEDD4L expression is also associated with the prognosis of patients with gastric cancer." (PMID 31673244, 2019). "Furthermore, treatment with 18β-GRA significantly decreased NEDD4L expression in gastric cancer cells, suggesting its potential as a diagnostic and therapeutic biomarker for the disease." (PMID 41561975, 2025). "Low expression of NEDD4L was found to be associated with poor survival of gastric cancer patients." (PMID 37291499, 2023). "The expression of IGF2BP3 increased with the progression of gastric cancer, while the expression of NEDD4L increased only in the early stage." (PMID 41561975, 2025). "The contrasting roles of NEDD4 and NEDD4L in gastric cancer metastasis highlight the complexity within the E3 ligase families and the requirement for specific targeting strategies." (PMID 41385185, 2025). "The clinical relevance analysis revealed NEDD4L’s prominent role, characterized by increased expression in early gastric cancer and EBV subtypes." (PMID 41561975, 2025). "Reduced expression of NEDD4L correlated with adverse prognosis in non-small cell lung cancer, gastric cancer, hepatocellular carcinoma, ovarian cancer, and malignant glioma." (PMID 34809620, 2021). "To date, it has been reported that the expression of NEDD4L is positively related to the outcomes of gastric cancer patients." (PMID 34869021, 2021). "Decreased expression of NEDD4L has been reported to correlate with poor prognosis in gastric cancer patient." (PMID 29324665, 2018). "Recently, NEDD4L protein levels were shown to be downregulated in gastric cancer, and those patients with the lowest expression by immunohistochemical analysis had a worse prognosis." (PMID 24312311, 2013). "Bioinformatics analyses revealed decreased EGR1 expression alongside increased NEDD4L expression in gastric cancer, suggesting EGR1 may bind the NEDD4L promoter to regulate its transcription." (PMID 41561975, 2025). "In summary, these findings suggest that 18β-GRA may regulate the progression of gastric cancer through the NEDD4L/SCN5A axis." (PMID 41561975, 2025). "In addition to TRIM family members, a previous study showed that E3 ubiquitin ligase NEDD4L (neural precursor cell expressed developmentally down-regulated 4-like) inhibits EMT process to prevent gastric cancer progression." (PMID 41385185, 2025). "Mechanistically, it was found that HIF-1α might be responsible for low-level expression of NEDD4L in gastric cancer." (PMID 41385185, 2025). "However, further experiments at the cellular and animal levels are needed to test the function of NEDD4L in gastric cancer development." (PMID 34869021, 2021). "In addition, a high level of NEDD4L generally corresponded to a low level of HIF-1α in gastric cancer tissues and led to a favorable prognosis." (PMID 34869021, 2021). "Collectively, NEDD4L might affect the metastasis of gastric cancer and together with HIF-1α, could predict the prognosis of patients." (PMID 34869021, 2021). "Our results indicate that the role of HIF-1α in gastric cancer is the opposite of NEDD4L." (PMID 31673244, 2019).
gastric cancer (continued). "This suggests that NEDD4L may be significant for the early clinical diagnosis of gastric cancer." (PMID 41561975, 2025). "Therefore, we hypothesize that 18β-GRA promotes SCN5A ubiquitination via NEDD4L to inhibit gastric cancer progression." (PMID 41561975, 2025). "However, NEDD4L has been observed to have contradictory roles, as it promotes cancer of gallbladder cancer and malignant glioma, and has a protective role in colorectal and gastric cancer." (PMID 31673244, 2019). "Intercellular adhesion molecule 2 (ICAM2), a transmembrane glycoprotein, can promote the NEDD4L-mediated ubiquitination and degradation of RDX, thereby inhibiting the tumorigenicity and metastasis of gastric cancer." (PMID 38027016, 2023). "Although studies have shown that Nedd4L may act as a tumor suppressor in various cancers, including gastric cancer (GC), its clinical significance and the diagnostic value in GC is not well defined." (PMID 31673244, 2019).